DUT (deoxyuridine triphosphatase)
Description:
Catalyzes the cleavage of 2'-deoxyuridine 5'-triphosphate (dUTP) into 2'-deoxyuridine 5'-monophosphate (dUMP) and inorganic pyrophosphate and through its action efficiently prevents uracil misincorporation into DNA and at the same time provides dUMP, the substrate for de novo thymidylate biosynthesis. Inhibits peroxisome proliferator-activated receptor (PPAR) activity by binding of its N-terminal to PPAR, preventing the latter's dimerization with retinoid X receptor (By similarity). Essential for embryonic development (By similarity).
Synonyms: dUTPase; BMFDMS
Tractability: Small molecule: a structure with a bound ligand is known; a high-quality ligand is known; it has a binding pocket of medium quality; it belongs to a druggable protein family. PROTAC: ubiquitination databases record sites on it; its protein half-life has been measured; a small molecule that binds it is known.
Target class: Enzyme; Hydrolase
Gene: Protein-coding gene on chromosome 15 (48,331,011 to 48,343,373, forward strand). Ensembl gene ENSG00000128951.
Subcellular location: Nucleus (Isoform 2); Mitochondrion (Isoform 3)
Subcellular location (Human Protein Atlas): Nucleoplasm
Pathways (Reactome):
Metabolism: Interconversion of nucleotide di- and triphosphates
Gene Ontology:
Molecular function: dUTP diphosphatase activity; protein binding; RNA binding; identical protein binding; magnesium ion binding; peroxisome proliferator activated receptor binding; pyrimidine deoxyribonucleotide binding; signaling receptor inhibitor activity
Biological process: dTMP biosynthetic process; DNA replication; dUMP biosynthetic process; dUTP catabolic process; nucleobase-containing compound metabolic process; liver development; pyrimidine deoxyribonucleoside monophosphate biosynthetic process; pyrimidine deoxyribonucleotide biosynthetic process; regulation of protein-containing complex assembly
Cellular component: extracellular exosome; mitochondrion; nucleoplasm; nucleus
Genetic constraint (gnomAD): Loss-of-function variants: 17 observed, 14.92 expected, observed/expected ratio (o/e) 1.14, 90% interval 0.78 to 1.68. The synonymous counts are far from expectation, so gnomAD's model fits this gene poorly and the ratio says little. Missense variants: 276 observed, 226.16 expected, observed/expected ratio (o/e) 1.22, 90% interval 1.11 to 1.35. Synonymous variants: 129 observed, 96.52 expected, observed/expected ratio (o/e) 1.34, 90% interval 1.16 to 1.55.
Homologues: Orthologues: chimpanzee DUT (98% identical), macaque DUT (93% identical), dog DUT (74% identical), pig DUT (70% identical), rat Dut (58% identical), guinea pig DUT (56% identical), mouse Dut (55% identical), tropical clawed frog dut (51% identical), zebrafish dut (46% identical), Caenorhabditis elegans dut-1 (44% identical), Drosophila melanogaster dUTPase (39% identical).
Diseases named in the same sentence as DUT in open-access papers:
DUT is named in the same sentence as 21 diseases in open-access papers, as found by Europe PMC text mining. Sharing a sentence is not in itself a finding about the gene and the disease. The quoted sentences say what the papers report.
bone marrow failure (4 papers, 2020 to 2025). "Recent studies have identified mutations in DUT as the primary cause of bone marrow failure and diabetes mellitus syndrome (BMFDMS), a condition commonly associated with thrombocytopenia." (PMID 40362420, 2025). "Recently, bi-allelic DUT (deoxyuridine triphosphatase [MIM: 601266]) variants that hydrolyses dUTP to dUMP in the de novo synthesis pathway were reported in individuals with bone-marrow failure associated with diabetes." (PMID 35931051, 2022). "DUT was published as a candidate for a novel syndromic form of diabetes involving bone marrow failure based on a single missense variant." (PMID 33456446, 2020). "For example, mutations in DUT, a key enzyme preventing the accidental incorporation of uracil to maintain DNA integrity, can lead to a kind of early-onset diabetes accompanied with bone marrow failure." (PMID 34820159, 2021).
breast carcinoma (3 papers, 2021 to 2025). "The expression of DGAT1, DUT, LYPLA1, and POLR2K was linked to an increased risk of breast cancer, whereas SMPD4 was associated with a protective effect." (PMID 37644433, 2023). "DUT expression was found to be significantly higher across all breast cancer subtypes in the analysis when compared to the adjacent normal tissue (P = 0.0005)." (PMID 33824328, 2021). "Indeed, DDR1i caused differential expression in several direct RUNX1 target genes including DUT, an essential nucleotide metabolism enzyme seen upregulated across breast cancers, and MYC, along with ANP32B, PLEC, CEBPD, ID1, and STAT3." (PMID 40614729, 2025). "Expression of DUT correlated with relapse-free survival (RFS) (P = 0.0051), however, this did not translate to a significant difference in OS (P = 0.07) across all breast cancer patients, similar to the previous data set analysed." (PMID 33824328, 2021).
cervical cancer (3 papers, 2019 to 2021). A primary or metastatic malignant neoplasm involving the cervix. "The aim of this study was to explore the distribution frequency of six single nucleotide polymorphisms (SNPs) in the dUTPase-encoding gene DUT in a case-control study to identify the relationship between DUT genetic variants and cervical cancer susceptibility." (PMID 30679536, 2019).
cervical intraepithelial neoplasia (2 papers, 2019 to 2020). "Six DUT intronic SNPs (rs28381106, rs3784619, rs10851465, rs28381126, rs3784621 and rs11637235) were genotyped by mismatch amplification-PCR in 400 cervical squamous cell carcinomas (CSCCs), 400 precursor cervical intraepithelial neoplasia (CIN) III lesions and 1,200 normal controls." (PMID 30679536, 2019).
viral infection (2 papers, 2010 to 2023). "In this population-based study, we found nine genes/regions associated with CIN3/cancer, 6 of which remained significant at a FDR≤0.2 – three DNA repair genes (GTF2H4, DUT, and DMC1) and three viral infection and cell entry related genes (OAS3, SULF1, and IFNG)." (PMID 20084279, 2010).
colon cancers (1 paper, 2022). "In addition, long-term treatment with 5FU leads to increased expression of thymidylate synthase (TS), Bcl-1, Bcl-XL and Mcl-1 as well as increased activity of deoxyuridine triphosphatase and methylation of MLH1, which are associated with 5FU resistant colon cancers (reviewed in 68)." (PMID 35910798, 2022).
colorectal cancer (1 paper, 2009). A primary or metastatic malignant neoplasm that affects the colon or rectum. "Overexpression of deoxyuridine triphosphatase nucleotide hydrolase (dUTPase) is also significantly associated with poor prognosis in colorectal cancer patients treated with 5-FU." (PMID 19052026, 2009).
Infertility (1 paper, 2022). "Furthermore, the Wilcox test revealed a significant association of RPS9, DUT, CDKN2C and MARF1 genes with infertility in the red, blue, and turquoise modules." (PMID 35603216, 2022).
lung adenocarcinoma (1 paper, 2021). A carcinoma that arises from the lung and is characterized by the presence of malignant glandular epithelial cells. "Using immunohistochemistry, the expression levels of PSMB6, HSPA9, DUT, CDK7, and PLK1 were found to be higher in lung adenocarcinoma tissues of patients, while the expression of FOLR2 was low, which was consistent with survival prediction." (PMID 34721732, 2021).
mental disorder (1 paper, 2018). A disease that has its basis in the disruption of mental process. "Table presents a distribution of combined genotypes of DUT rs4775748, SMUG rs3087404 and UNG rs34259 single-nucleotide polymorphisms, and OR with 95% CI in groups of patients with rDD and controls without mental disorders." (PMID 29967751, 2018). "Table presents a distribution of genotypes and alleles of DUT g.48346598G>T (rs4775748), SMUG1 c.-31A>G (rs3087404) and UNG g.7245G>C (rs34259) single-nucleotide polymorphisms, and OR with 95% CI in groups of patients with rDD and controls without mental disorders." (PMID 29967751, 2018).
myeloma (1 paper, 2024). "In bortezomib-resistant myeloma cells, there is an increased level of DUT, an important enzyme involved in nucleotide metabolism." (PMID 39159158, 2024).
Pancytopenia (1 paper, 2022). An abnormal reduction in numbers of all blood cell types (red blood cells, white blood cells, and platelets). "In our exomes, we also identified probands who came from two independent families, had bi-allelic DUT variants, and presented with severe pancytopenia and mucocutaneous skin features." (PMID 35931051, 2022).
Thrombocytopenia (1 paper, 2025). A reduction in the number of circulating thrombocytes. "In conclusion, the DUT (p.Y116C)-mutant rabbit model serves as a reliable and novel model for studying thrombocytopenia associated with DUT dysfunction." (PMID 40362420, 2025). "Despite the critical role of DUT as an essential gene, its specific association with thrombocytopenia remains poorly understood." (PMID 40362420, 2025). "Considering the link between thrombocytopenia and DUT mutations, and the fact that platelets are derived from megakaryocyte fragmentation, we further explored the relationship between DUT and megakaryocytes." (PMID 40362420, 2025). "This study presents the first genetic model of thrombocytopenia that closely mimics the human DUT (p.Y116C) mutation, offering new insights into the relationship between DUT mutations and platelet function, and highlighting potential therapeutic targets for human thrombocytopenia." (PMID 40362420, 2025).
tumor (9 papers, 2009 to 2025). "Deoxyuridine triphosphatase inhibitor has achieved significant clinical effects in many clinics and is currently a promising tumor-targeted therapy drug." (PMID 34354842, 2021). "High levels of DUT protein expression are predictive for tumor resistance to chemotherapy in colorectal cancer." (PMID 26202601, 2015). "The present study shows, for what is believed to be the first time, that expression of deoxyuridine triphosphatase (dTUPase) was augmented in metastasis as compared with the primary tumour in colon." (PMID 19052026, 2009). "The overexpression of PSMB6, HSPA9, DUT, CDK7, and PLK1 was seen in resected tumor tissues compared with adjacent normal tissues, while FOLR2 was expressed more in normal tissues." (PMID 34721732, 2021). "As expected, genes involved in cell-cycle and nucleotide metabolism, such as DUT and MCM5, were required for tumor growth." (PMID 32579974, 2020).
cancer (5 papers, 2010 to 2024). A tumor composed of atypical neoplastic, often pleomorphic cells that invade other tissues. "Five genes, UNG, SMUG1, MBD4, TDG, and DUT, are involved in the repair and prevention of uracil misincorporation into DNA, an anomaly that can lead to cancer-causing mutations." (PMID 30679536, 2019). "To date, no studies have been performed to investigate the correlation between SNPs of the DUT gene and cancer susceptibility." (PMID 30679536, 2019). "This suggests that DUT SNPs may influence cancer risk because elevated uracil misincorporation may induce mutagenic lesions." (PMID 30679536, 2019). "DUT and NT5C are enzymes involved in nucleotide metabolism and are associated with the prognosis of cancer patients." (PMID 34885971, 2021). "From each region, the single most significant SNPs associated with CIN3/cancer were OAS3 rs12302655, SULF1 rs4737999, IFNG rs11177074, DUT rs3784621, DMC1 rs5757133, GTF2H4 rs2894054, EVER1/EVER2 rs9893818 (p-trends≤0.001)." (PMID 20084279, 2010). "SNPs for OAS3, SULF1, DUT, and GTF2H4 were associated with HPV persistence whereas IFNG and EVER1/EVER2 SNPs were associated with progression to CIN3/cancer." (PMID 20084279, 2010). "TDRD10 and DUT expression have both been linked with poor survival in cancer, but have never previously been studied in EC." (PMID 32899298, 2020). "However, TYMS, DUT, POLB, LIG1 and FEN1 have been identified by others as PARGi synthetic lethality genes, and these observations support the notion that inhibition of nucleotide biosynthesis and BER can sensitize cancer cells to pharmacological PARG inhibition." (PMID 39015544, 2024).
infection (1 paper, 2022). The state of being infected such as from the introduction of a foreign agent such as serum, vaccine, antigenic substance or organism. "We then used RT-qPCR to probe the base line expression levels of key UBER enzymes (UNG, APE1, pol β, lig III, DUT) and the dNTPase SAMHD1 in AM and MDM prior to infection with HIV." (PMID 36114511, 2022).
DUT also shares sentences with these, for which no sentence is quoted: diabetes (3 papers); tongue squamous cell carcinoma (2); cervical squamous cell carcinoma (1); depression (1); non-small cell lung carcinoma (1).